GPR62 (G protein-coupled receptor 62)
Description:
Orphan G protein-coupled receptor. Constitutively activates the G(q/11)/inositol phosphate and the G(s)-alpha/cAMP signaling pathways. Has spontaneous activity for beta-arrestin recruitment. Shows a reciprocal modulation of signaling functions with the melatonin receptor MTNR1B most likely through receptor heteromerization.
Synonyms: GPCR8; KPG_005
Tractability: Small molecule: it belongs to a druggable protein family. Antibody: UniProt places it where antibodies can reach, with high confidence; its Gene Ontology location is reachable by antibodies, with high confidence; UniProt predicts a signal peptide or a membrane-spanning region.
Target class: Family A G protein-coupled receptor; Membrane receptor
Gene: Protein-coding gene on chromosome 3 (51,955,381 to 51,957,499, forward strand). Ensembl gene ENSG00000180929.
Subcellular location: Cell membrane; Endosome membrane
Gene Ontology:
Molecular function: arrestin family protein binding; protein binding; G protein-coupled receptor activity; identical protein binding
Biological process: ligand-independent adenylate cyclase-activating G protein-coupled receptor signaling pathway; positive regulation of calcium-mediated signaling; adenylate cyclase-activating G protein-coupled receptor signaling pathway; G protein-coupled receptor signaling pathway
Cellular component: endosome; endosome membrane; plasma membrane; receptor complex; membrane
Genetic constraint (gnomAD): Loss-of-function variants: 1 observed, 0.28 expected, observed/expected ratio (o/e) 3.61. That is too few expected variants to judge how well the gene tolerates losing a copy. Missense variants: 316 observed, 248.87 expected, observed/expected ratio (o/e) 1.27, 90% interval 1.16 to 1.39. Synonymous variants: 158 observed, 121.86 expected, observed/expected ratio (o/e) 1.3, 90% interval 1.14 to 1.48.
Homologues: Orthologues: macaque GPR62 (96% identical), pig GPR62 (86% identical), dog GPR62 (85% identical), guinea pig GPR62 (83% identical), rat Gpr62 (80% identical), mouse Gpr62 (79% identical). Paralogues in human: GPR61 (33% identical), GPR135 (21% identical), GPR176 (17% identical).
Diseases named in the same sentence as GPR62 in open-access papers:
GPR62 is named in the same sentence as 1 disease in open-access papers, as found by Europe PMC text mining. Sharing a sentence is not in itself a finding about the gene and the disease. The quoted sentences say what the papers report.
cancer (1 paper, 2019). A tumor composed of atypical neoplastic, often pleomorphic cells that invade other tissues. "In urine DNA, some markers like HOXD3, HOXA7, GPR62 and KLK10 were detected with comparable frequency from all cancer patients and are candidates for biomarker panels used for the early detection of PCA." (PMID 31297302, 2019).